GPR15 (G protein-coupled receptor 15)
Diseases named in the same sentence as GPR15 in open-access papers (continued):
Sharing a sentence is not in itself a finding about the gene and the disease.
co-infection (1 paper, 2014). "An explanation for the observed GPR15 increase in a subset of HIV-1 infected patients could be potential co-infection with another virus which may lead to additional TLR3 triggering followed by GPR15 increase." (PMID 24558379, 2014).
colon polyps (1 paper, 2023). "Interestingly, the colon polyps (LIP) in the AOM-DSS treated Gpr15-KO mice showed distinct (e.g., increased MDSCs) as well as shared (e.g., increased IL-17A+ CD4+ and IL-17A+ CD8+ T cells) immune features of human CRC with reduced GPR15 expression." (PMID 38074634, 2023). "In line with our hypothesis, we observed severe, widespread inflammation in the colon along with increased incidence of colon polyps/tumors in the Gpr15-KO group compared to Gpr15-Het group in both early and late phases of disease development (Day 24-66) post AOM-DSS administration." (PMID 38074634, 2023). "Importantly, Gpr15-KO mice showed significant body weight loss during disease progression, lower survival rate, more colon polyps (of size > 2mm) in the middle and distal colon (measured at week 10), and shorter colon length (measured at week 10) than Gpr15-Het mice." (PMID 38074634, 2023). "Analysis of immune cell infiltrates in the colonic polyps showed significantly decreased CD8+ T cells and increased IL-17+ CD4+ and IL-17+ CD8+ T cells in Gpr15-KO than in Het mice." (PMID 38074634, 2023). "Interestingly, the colon polyps (LIP) in the AOM-DSS treated Gpr15-KO mice showed distinct (e.g., expansion of MDSCs) as well as shared (e.g., increased IL-17+ CD4+ and IL-17+ CD8+ T cells) immune features of human CRC with reduced GPR15 expression." (PMID 38074634, 2023).
COVID-19 (1 paper, 2021). A disease caused by infection with severe acute respiratory syndrome coronavirus 2. "We observed no significant change of GPR15 expression in patients with active or after COVID-19 on CD4+ memory T cells." (PMID 33959123, 2021).
gastric cancer (1 paper, 2023). A primary or metastatic malignant neoplasm involving the stomach. "In this study, the gastric cancer patients with high expression of CTLA4 and ENTPD2 had a better survival prognosis, with high expression of CLDN6, EMB, GPR15, VWF and AKR1B1 suggesting poor prognosis, which was consistent with previous studies." (PMID 37066015, 2023).
gastric tumor (1 paper, 2023). "Compared with benign tissues, the CTLA4 and ENTPD2 were highly expressed in gastric tumor tissues, while the AKR1B1, CLDN6, EMB, GPR15 and VWF were highly expressed." (PMID 37066015, 2023).
Graves disease (1 paper, 2022). Graves' disease is an autoimmune disorder that leads to overactivity of the thyroid gland (hyperthyroidism).It is caused by an abnormal immune system response that causes the thyroid gland to produce too much thyroid hormones. "To determine whether GPR15 expression in PBMCs was independently associated with Graves’ disease, we conducted a multinomial logistic regression analysis while controlling for potential confounding factors (age and sex)." (PMID 36551327, 2022). "To further investigate the effect of GPR15 on Graves’ disease, we expanded the sample size." (PMID 36551327, 2022). "Yet, no study on the association between GPR15 and Graves’ disease (GD) is available." (PMID 36551327, 2022).
Hashimoto thyroiditis (1 paper, 2022). An autoimmune disorder caused by the production of autoantibodies against thyroid tissue. "In our previous animal experiment, by transcriptome sequencing, we accidentally found that GPR15 expression was increased in the thyroid tissue of Hashimoto’s thyroiditis model mice." (PMID 36551327, 2022). "We found that GPR15 mRNA expression in PBMC was not different in Hashimoto’s thyroiditis patients compared with healthy donors (p > 0.05), but increased in GD patients." (PMID 36551327, 2022).
heart failure (1 paper, 2024). Inability of the heart to pump blood at an adequate rate to meet tissue metabolic requirements. "Moreover, the GPR15-mediated migration of TC cells is essential for virus elimination in viral myocarditis to prevent progression to heart failure." (PMID 39195892, 2024). "We examined the regulation of GPR15 in various heart failure entities." (PMID 39195892, 2024).
HIV-1 infection (1 paper, 2014). The type species of lentivirus and the etiologic agent of acquired immunodeficiency syndrome (AIDS). "We found that GPR15 expression was up-regulated ex vivo on CD4+ T cells in two out of eleven HIV-1 patients, that HIV-1 infection can upregulate GPR15 in PM1 T cells and that TLR3 triggering by dsRNA up-regulated GPR15 expression on CD4+ T cells." (PMID 24558379, 2014). "For all three virus isolates the expression of GPR15 was markedly higher on infected compared to uninfected PM1 cells, as determined by co-staining of intracellular HIV-1 p24, suggesting that HIV-1 infection up-regulates GPR15 expression." (PMID 24558379, 2014). "To investigate if HIV-1 infection can up-regulate GPR15 surface expression we chose the PM1 T cell line as a model system.." (PMID 24558379, 2014). "To investigate whether GPR15 expression on these T cell subsets is altered in the context of HIV-1 infection, we analyzed surface expression of GPR15 on CCR7+CD45RA− central memory, CCR7−CD45RA− effector memory and CCR7+CD45RA+ naïve CD4+ T cells from healthy donors and HIV-1 infected individuals." (PMID 24558379, 2014). "In addition we observed that upon in vitro HIV-1 infection, PM1 T cells showed increased GPR15 levels on the productively infected cells suggesting a role of viral components in up-regulating GPR15 expression." (PMID 24558379, 2014). "Thus, among CD4-positive T cells, the TLR3 induced up-regulation of GPR15 expression is largely specific for gut homing CD4+ T cells and might broaden the target cell availability during HIV-1 infection in the gut." (PMID 24558379, 2014). "However, it has not been determined whether GPR15 expression is altered in the context of HIV-1 infection." (PMID 24558379, 2014). "However, the impact of TLR activation on GPR15 expression has not been determined and it is unknown if GPR15 expression is altered in the context of HIV-1 infection." (PMID 24558379, 2014).
intestinal tumors (1 paper, 2023). "G protein-coupled receptor 15 (GPR15) is an unconventional chemokine receptor that mediates Treg homing and immunosuppression by directing Treg into the colon, thereby altering the tumor microenvironment and promoting occurrence of intestinal tumors." (PMID 37066015, 2023).
Lyme disease (1 paper, 2016). Lyme disease (named after the towns in the USA where the disease was first identified) is a bacterial infection caused by Borrelia burgdorferi. "A single DEG (GPR15) was found at V1 when patients with resolved Lyme disease (n = 15) were compared with patients with PTLDS (n = 4)." (PMID 26873097, 2016). "When all of the time points were combined, a total of four different DEGs overall were identified in Lyme disease patients with persistent symptoms (non-PTLDS and/or PTLDS) compared to those with resolved disease, i.e., MIAT, CCDC163P, ZNF266, and GPR15." (PMID 26873097, 2016).
myocarditis (1 paper, 2024). Myocarditis is a condition that is characterized by inflammation of the heart muscle (myocardium). "Employing GPR15-deficient mice, we investigated the subacute phase (16 days p.i.)and found that GPR15 deficiency affected the outcome of CVB3-induced myocarditis." (PMID 39195892, 2024). "So far, the previous results point toward alterations in chemotaxis and cardiac inflammation, particularly associated with T cells, in GPR15-deficient mice during myocarditis." (PMID 39195892, 2024). "The here-observed late sequela of myocarditis by GPR15 deficiency might be traced back to delayed recruitment of Treg cells, but possibly also TC cells, into the virus-infected myocardium." (PMID 39195892, 2024). "To elucidate the patho-mechanistical function of GPR15 during myocarditis, we thoroughly investigated its acute phase (5 days, 6 days and 7 days p.i.)." (PMID 39195892, 2024). "Regarding the results of the GO analysis, which particularly highlighted chemotaxis, we hypothesized that GPR15 may function as a chemokine receptor mediating T cell homing during myocarditis." (PMID 39195892, 2024). "Therefore, our experiments strengthen the hypothesis that GPR15 is essential for the recruitment of T cells to the site of inflammation in the acute phase of CVB3-induced myocarditis." (PMID 39195892, 2024).
neutropenia (1 paper, 2014). A decrease in the number of neutrophils found in the blood. "GPR15/BOB is highly expressed on the surface of neutrophils from Chinese rhesus macaques and its ligation during early SIV infection induces neutrophil death and is associated with neutropenia and disease progression." (PMID 24725539, 2014).
osteosarcoma (1 paper, 2021). A usually aggressive malignant bone-forming mesenchymal neoplasm, predominantly affecting adolescents and young adults. "It has been shown that this fragment inhibits the entry of GPR15-tropic derivatives of HIV and SIV in human osteosarcoma (GHOST) cells that stably express CD4 and GPR15." (PMID 34639163, 2021).
polyp (1 paper, 2023). A usually exophytic mass attached to the underlying tissue by a broad base or a thin stalk. "Gpr15-Het and Gpr15-KO mice that were not treated with AOM-DSS showed no polyp formation and had similar survival rates, while C57BL/6 WT mice treated with AOM-DSS demonstrated similar disease course/severity and survival rates as Gpr15-Het mice." (PMID 38074634, 2023).
smoking (1 paper, 2019). "G protein-coupled receptor 15 (GPR15, also known as BOB) is an extensively studied orphan G protein-coupled receptors (GPCRs) involving human immunodeficiency virus (HIV) infection, colonic inflammation, and smoking-related diseases." (PMID 31835584, 2019).
viral myocarditis (1 paper, 2024). Myocarditis that is caused by an infection with a viral agent. "Therefore, GPR15-deficient mice were investigated in the context of CVB3-induced viral myocarditis." (PMID 39195892, 2024). "In conclusion, we identified GPR15 as a chemokine receptor crucial for a better outcome after acute viral myocarditis." (PMID 39195892, 2024). "In this study, we examined the consequences of GPR15 deficiency on development, progression and recovery in experimental CVB3-induced viral myocarditis." (PMID 39195892, 2024). "Therefore, we aimed to examine the role of GPR15 during viral myocarditis." (PMID 39195892, 2024).
infection (13 papers, 2010 to 2024). The state of being infected such as from the introduction of a foreign agent such as serum, vaccine, antigenic substance or organism. "Infection of the PM1 T cell line with different HIV-1 primary isolates showed that GPR15 expression can be up-regulated in productively infected cells." (PMID 24558379, 2014). "In the case of HIV mono-infection, gene GPR15 together with 7 other transcript IDs were found to be differently expressed when compared to the HCV mono-infections or to the HIV/HCV co-infections." (PMID 23028845, 2012). "This same promiscuity has been investigated for the HIV-1 envelope, and it was revealed that the chemokine receptors CCR2b, CCR3, CCR7, CCR8, STRL33/BONZO, and gpr15/BOB can mediate infection of cells by some viruses." (PMID 21994672, 2010). "This suggests that infection induced TLR3 stimulation could increase GPR15 homing of T cells to the gut thereby increasing the target cell availability and facilitating viral dissemination." (PMID 24558379, 2014). "This suggested that the ZP6248 tropism for GPR15 was mainly determined by the V3 although sequences outside V3 might be also required for optimal infection of GPR15+ cells." (PMID 24897520, 2014). "However, all those unique amino acids together in ZP6248 V3 were critical in mediating infection thorough the use of GPR15." (PMID 24897520, 2014). "The up-regulation of GPR15 could support infection, more likely super-infection as well as viral dissemination." (PMID 24558379, 2014). "The increase in GPR15 expression may allow better entry and infection of HIV in the HIV/HCV co-infected patients than in the HIV mono-infected ones." (PMID 23028845, 2012). "Of note, both CXCR6 and GPR15 are also highly expressed in intestinal tissues, raising the question of whether alternative coreceptor use may be involved in mucosal events that play a central role in infection." (PMID 20865163, 2010). "The orphan 7-transmembrane receptor GPR15 is used by many HIV-2 and SIV strains, as well as some HIV-1 isolates for efficient infection of co-receptor transfected cell lines." (PMID 24558379, 2014). "GPR15/BOB and CCR5 share a sequence of three tyrosine residues in the amino-terminal region, which if altered in CCR5, results in decreased efficiency of infection by SIV and macrophage-tropic human immunodeficiency virus (HIV)-1 strains." (PMID 24725539, 2014). "We therefore tested the ability of SIVsmm envelopes to mediate infection through human CCR2b, CCR3, CCR8, GPR1, GPR15 (BOB), CXCR6 and CXCR4." (PMID 20865163, 2010). "Since the gut mucosal homing receptor α4β7-integrin binds to HIV-1 and might be important for productive infection of CD4+ T cells, we next investigated whether GPR15 positive lymphocytes co-express gut (α4β7-integrin) and lymph node (CD62L) homing receptors." (PMID 24558379, 2014). "In contrast to all other HIV-1 T/F viruses that use either CCR5 and/or CXCR4 coreceptors for entry, the T/F virus ZP6248 established the clinical infection most likely used the coreceptor GPR15 and the unique V3 crown GPEK in ZP6248 play a critical role in the GPR15 tropism." (PMID 24897520, 2014). "Infection of the PM1 T cell line with primary HIV-1 isolates was found to up-regulate GPR15 expression on the infected cells, indicating that viral components can induce GPR15 expression." (PMID 24558379, 2014). "No appreciable change in total GPR15 expression was observed on non-infected cells upon infection with the multitropic HIV-1 isolates 25, 4054 and the R5 tropic isolate 2195." (PMID 24558379, 2014). "Thus, CXCR6 and GPR15 are particularly likely candidates for mediating SM infection independent of CCR5, and further studies are required to determine which one or ones are responsible for entry into primary SM PBMC ex vivo and infection in vivo." (PMID 20865163, 2010).
infection (continued). "However, we recently identified a transmitted/founder (T/F) virus (ZP6248) that efficiently used an alternative coreceptor GPR15, rather than commonly used CXCR4 and CCR5, to establish clinical infection." (PMID 24897520, 2014).
tumor (12 papers, 2017 to 2023). "In an AOM-DSS mouse model of CAC, GPR15 deficiency resulted in increased tumor burden, morbidity, and mortality concomitant with reduced T cell infiltration (especially CD8+ T cells) in the tumor microenvironment." (PMID 38074634, 2023). "They identified a specific set of genes that are preferentially expressed in tumor-associated Tregs, including GPR15." (PMID 37457732, 2023). "To support these findings, we investigated the association between GPR15 expression levels and immune cell infiltration levels in the tumor microenvironment using TIMER." (PMID 31835584, 2019). "Similarly, we found that the expression of GPR15 was positively associated with the levels of tumor-infiltrating immune B cells and DCs and predicted that GPR15 could interact with DC-related CXCL12 to participate in RC progression." (PMID 33833937, 2021). "In the AOM-DSS CAC model, GPR15 deficiency was similarly associated with unique alterations in the composition of immune subsets in the tumor (LIP) and non-tumor (LI) regions of the colon as well as in secondary lymphoid organs." (PMID 38074634, 2023). "Our analysis of human CRC tissue revealed a significant reduction in GPR15+ immune cell frequencies in tumors compared to ‘tumor-free’ surgical margins." (PMID 38074634, 2023). "Our analysis revealed significantly reduced GPR15 mRNA expression in tumors compared to tumor adjacent normal tissue in COAD." (PMID 38074634, 2023). "In this report, we delineate a novel tumor-suppressive function of GPR15 using CRC mouse models and patient samples." (PMID 38074634, 2023). "The decreased infiltration of CD8+ T cells and expanded MDSC population observed in the tumors (LIP) of AOM-DSS treated Gpr15-KO mice are common denominators in tumor formation and progression in several cancers including CRC." (PMID 38074634, 2023). "The enrichment of such inflammatory and immune-suppressive phenotypes in the AOM-DSS Gpr15 KO group is coincident with increased tumor burden in this group." (PMID 38074634, 2023). "Our findings in the AOM-DSS CAC model lend credence to GPR15 involvement in recruitment of T cells with tumor-suppressive function to the colon and aiding in the evolution of an immune environment unfavorable for tumor growth." (PMID 38074634, 2023). "MC38 cells were injected subcutaneously in Gpr15-Het and -KO mice, and tumor development was monitored following concomitant intratumoral injection of GPR15L or vehicle (PBS) when tumors reached 4-5 mm in size (Day 4 post-transplant)." (PMID 38074634, 2023). "Our results indicate that both GPR15 expression (reported as mean fluorescence intensity; MFI) and the frequency of GPR15+ CD45+ immune cells was decreased in the tumor tissue compared to STM." (PMID 38074634, 2023). "We found that the GPR15 expression value was significantly negatively correlated with tumor purity in all four types of cancer." (PMID 31835584, 2019). "In sum, our studies provide ‘proof-of-concept’ for the therapeutic targeting of GPR15-GPR15L axis in CRC treatment; intratumoral administration of GPR15L attenuates tumor growth in a GPR15-dependent manner by shaping an anti-tumor immune environment enriched in cytolytic T, NK and NKT cells." (PMID 38074634, 2023). "To further delineate the role and explore the translational relevance of our findings, we examined if GPR15 agonism by GPR15L administration would elicit an anti-tumor effect by influencing immune cell phenotypes and their functionality in the MC38-murine CRC model." (PMID 38074634, 2023). "Based on our observation that GPR15+ T cells are reduced in the tumor microenvironment in human CRC, we posited that GPR15 deficiency would result in enhanced disease susceptibility and severity in part by influencing T cell infiltration to the colon in the AOM-DSS model of CAC." (PMID 38074634, 2023).